ING5 (inhibitor of growth family member 5)
Diseases named in the same sentence as ING5 in open-access papers (continued):
Sharing a sentence is not in itself a finding about the gene and the disease.
ovarian carcinoma (continued). "To further validate the relationship between miR-1307 and ING5 in ovarian cancer cells, we detected the level of ING5 protein expression following different miR-1307 treatment in various kinds of ovarian cancer cells by western blot." (PMID 28086946, 2017). "ING5 expression was examined in ovarian cancer, and compared with the clinicopathological parameters to explore the roles of ING5 expression." (PMID 29262575, 2017). "miR‐1307 is an important anti‐apoptotic oncoprotein, known to promote chemotherapy resistance in ovarian cancer by targeting ING5 expression, and miR‐1307 may be a therapeutic target for ovarian cancer." (PMID 39183444, 2024). "In ovarian cancer cells, miR-200b/200a/429 targets ING5 which blocks miR-200b/200a/429-induced malignant transformation, and miR-1307 targets and down-regulated ING5 expression." (PMID 36425530, 2022). "In addition, ING5 can block the stimulating effects of miR-200b/200a/429 on proliferation and clone formation of ovarian cancer cells." (PMID 35747809, 2022). "There was an adverse relationship between ING5 mRNA expression and the overall or progression-free survival of the ovarian cancer patients with stage I, Grade 3, and Grade 2, indicating the prognostic significance of ING5 depends on the cancer type, subtyping and molecular level." (PMID 36425530, 2022). "ING5 immunoreactivity was less expressed in ovarian mucinous and serous adenocarcinoma than miscellaneous subtypes, and negatively correlated with differentiation and low ki-67 expression of ovarian cancer." (PMID 36425530, 2022). "Our findings suggest that miR-200b/200a/429 may be a useful biomarker for the early detection of ovarian cancer and that miR-200b/200a/429 significantly contributes to ovarian cancer development through ING5." (PMID 32377191, 2020). "The methods by analyzing the mechanism were similar with the recent reports, and our results indicated that miR-1307 could promote ovarian cancer chemoresistance by targeting ING5." (PMID 28086946, 2017). "Finally, we proved the inhibiting effect of miR-1307 ASO and Taxol therapy by increasing the ING5 expression against ovarian cancer through xenografts assay in vivo." (PMID 28086946, 2017). "In conclusion, our data suggested that miR-1307 could promote ovarian cancer chemoresistance by targeting the ING5 expression and miR-1307 might serve as a therapeutic target for ovarian cancer." (PMID 28086946, 2017). "Therefore, ING5 should be considered as a novel biomarker for ovarian carcinogenesis and a molecular target of gene therapy for ovarian cancer." (PMID 29262575, 2017). "Our study hinted that altered ING5 expression might impact on the malignant transformation of ovarian cancer cells and should be identified with a good biomarker for ovarian carcinogenesis." (PMID 29262575, 2017). "In spite of these the correlation between ING5 and ovarian cancer still remained unclear." (PMID 28086946, 2017). "The results indicated that miR-1307 directly targeted ING5 in ovarian cancer cells." (PMID 28086946, 2017). "Besides, we demonstrated that ING5 was a direct target of miR-1307 and miR-1307 down-regulated the ING5 expression in ovarian cancer cells." (PMID 28086946, 2017). "Immunohistochemically, ING5 was less expressed in serous and mucinous adenocarcinoma than miscellaneous subtypes, and positively correlated with dedifferentiation and ki-67 expression of ovarian cancer (p < 0.05)." (PMID 29262575, 2017). "Moreover, we confirmed that the inhibitor of growth 5 (ING5) as a functional target of miR-1307 in ovarian cancer cells." (PMID 28086946, 2017). "In summary, these results suggested that miR-1307 could promote the chemoresistance development of ovarian cancer by targeting ING5 in vitro." (PMID 28086946, 2017). "In short, ING5 overexpression suppressed the proliferation, energy metabolism, migration, invasion and tumor growth, but induced apoptosis, autophagy, senescence, and drug resistance of ovarian cancer cells." (PMID 29262575, 2017).
ovarian carcinoma (continued). "Here, we found that ING5 overexpression suppressed cell viability, glucose metabolism, migration, invasion and epithelial-mesenchymal transition, and induced cell arrest, apoptosis, senescence, autophagy and fat accumulation in ovarian cancer cells." (PMID 29262575, 2017). "Our results suggested that miR-1307 could promote ovarian cancer chemoresistance by targeting the ING5 expression and miR-1307 might serve as a therapeutic target for ovarian cancer." (PMID 28086946, 2017). "As shown in the present study, we could see the inhibiting effect of miR-1307 ASO by increasing the ING5 expression against chemoresistant ovarian cancer in vitro." (PMID 28086946, 2017). "Aberrant fat accumulation in ING5 transfectants might be attributable to the up-regulatory effect of ING5 on ADFP expression in ovarian cancer cells." (PMID 29262575, 2017). "Taken together, miR-1307 could down-regulate the ING5 expression in ovarian cancer cells." (PMID 28086946, 2017). "In line with other reports, we found that ING5 overexpression suppressed cell proliferation, tumor growth, glucose and lipid metabolism, and induced cell cycle arrest, apoptosis, senescence, and autophagy of ovarian cancer cells, even highly-invasive or paclitaxel-resistant ones." (PMID 29262575, 2017). "Finally, our results indicated miR-1307 could promote ovarian cancer chemoresistance by reducing the ING5 expression in vitro and in vivo." (PMID 28086946, 2017). "Regardless of cytoplasmic or nuclear distribution, ING5 was less expressed in serous and mucinous adenocarcinoma than miscellaneous subtypes, and positively correlated with dedifferentiation and ki-67 expression of ovarian cancers (p < 0.05)." (PMID 29262575, 2017). "However, the mechanism of ING5 in ovarian cancer development is not clear and needs further study." (PMID 32377191, 2020).
hepatocellular carcinoma (7 papers, 2015 to 2026). A malignant tumor that arises from hepatocytes. "Therefore, miR-331-3p promoted tumorigenesis of hepatoma cells in vivo by regulating ING5 expression." (PMID 26497554, 2015). "However, its antitumor mechanisms regarding of ING5 in hepatocellular carcinoma (HCC) remain unclear." (PMID 39247819, 2024).
head and neck cancer (6 papers, 2014 to 2023). A primary or metastatic malignant neoplasm affecting the head and neck. "ING5 is predicted to be one of the target genes which is linked to tumorigenesis in human head and neck carcinoma." (PMID 24573402, 2014). "CAFs secreted exosomal miR-196a to cancer cells, targeting CDKN1B and ING5 and mediating cisplatin resistance in head and neck cancer." (PMID 36319622, 2022). "Similarly, ING5 is a target gene of miR-196a and suppresses head and neck cancer cell survival and proliferation." (PMID 31844418, 2019).
bladder cancer (5 papers, 2015 to 2022). "ING5 overexpression was seen in chemosensitive bladder cancer cells, and ING5 silencing enhanced the chemoresistance, opposite to our findings." (PMID 35747809, 2022). "Recently, a report suggested that miR-193a-3p-regulated ING5 gene activated the DNA damage response pathway and inhibited multi-chemoresistance in bladder cancer." (PMID 28086946, 2017). "Reportedly, ING5 had an inhibitory effect on the chemoresistance of bladder cancer and inhibited the DNA damage response pathway." (PMID 29137236, 2017). "Reportedly, ING5 suppressed bladder cancer chemoresistance and DNA damage response pathway." (PMID 29262575, 2017).
glioma (5 papers, 2017 to 2023). A benign or malignant brain and spinal cord tumor that arises from glial cells (astrocytes, oligodendrocytes, ependymal cells). "Down-regulated ING5 expression might be closely linked the tumorigenesis of glioma, and its overexpression with the histogenesis of anaplastic astrocytoma." (PMID 28915612, 2017). "Down-regulated ING5 expression was closely linked to the tumorigenesis and histogenesis of glioma." (PMID 28915612, 2017). "In the present study, lower cytoplasmic and nuclear expression of ING5 in a large number of glioma cases suggested that its down-regulation promoted the tumorigenesis of glioma." (PMID 28915612, 2017). "Here, we found that ING5 up-regulated the Claudin 1 expression, but down-regulated the expression of N-cadherin, Slug, Snail, Twist, Zeb1 and Zeb2, indicating that ING5 suppressed the EMT in glioma." (PMID 28915612, 2017). "To elucidate the anti-tumor effects and molecular mechanisms of ING5 on glioma cells, we overexpressed it in U87 cells, and examined the phenotypes and their relevant molecules." (PMID 28915612, 2017). "Here, we observed the effects of ING5 overexpression on the anti-tumor and relevant molecular mechanisms of glioma cells." (PMID 28915612, 2017). "A lower expression of cytoplasmic and nuclear ING5 was for the first time observed in gliomas than normal brain tissues." (PMID 28915612, 2017). "Another study assessed the role of ING5 in cellular senescence in glioma cells." (PMID 35804879, 2022). "In line with the other reports, we found that ING5 overexpression inhibited proliferation, glycometabolism, invasion and migration, induced apoptosis, cell cycle arrest, senescence and differentiation of glioma cells." (PMID 28915612, 2017). "In combination of these findings, we hypothesized that ING5 might reverse the aggressive phenotypes of glioma cells and be employed as a potential target for gene therapy of glioma." (PMID 28915612, 2017). "Additionally, ING5 also suppressed the tumor growth of glioma by inhibiting proliferation and inducing apoptosis in tumor-bearing nude mice, in agreement with our in vitro data." (PMID 28915612, 2017). "Tumourigenesis and histogenesis of gliomas are modulated by ING5, a tumour suppressor; its overexpression decreases the level of Snail, Slug, Twist1, ZEB1 and ZEB2 in glioma cells and inhibited tumour growth in a xenograft mouse model." (PMID 37239035, 2023). "ING5 overexpression reduced proliferation, glycolytic function and mitochondrial respiration, and alkaline phosphatase (ALP) activity of glioma cells (p < 0.05)." (PMID 28915612, 2017). "Taken together, it was suggested that the activating effects of ING5 on both PI3K/Akt and β-catenin/TCF-4 signal pathways contributed to chemotherapeutic resistance in glioma cells." (PMID 28915612, 2017). "ING5 expression was lower in gliomas than that in normal brain tissue regardless of its subcellular expression pattern (p < 0.05)." (PMID 28915612, 2017). "In summary, ING5 overexpression might suppress the proliferation, energy metabolism, migration, invasion, EMT and tumor growth, and induce apoptosis and chemotherapeutic resistance of glioma cells." (PMID 28915612, 2017).
glioblastoma (4 papers, 2015 to 2024). The most malignant astrocytic tumor (WHO grade IV). "In particular, ING5 was found to be highly expressed in stem cells which promotes self-renewal of brain tumor initiating cells, which typically lead to glioblastomas." (PMID 37953885, 2023). "A higher expression of cytoplasmic or nuclear ING5 was detected in anaplastic astrocytoma than astrocytoma and glioblastoma (p < 0.05)." (PMID 28915612, 2017). "Then, we used Lee’s, Bredel’s, Sun's and Murat's dataset to perform bioinformatics analysis and found that ING5 mRNA expression was higher in glioblastoma than normal brain tissue from the results of the latter two investigators (p < 0.05)." (PMID 28915612, 2017). "Additional evidence for cell cycle dependent T152 phosphorylation of ING5 was obtained in T98A glioblastoma cells." (PMID 25860957, 2015). "In contrast, ING5 promoted the stemness and self-renewal of glioblastoma stem cells for tumor resistance and recurrence in glioblastoma by the activation of transcription of calcium channels and the follicle stimulating hormone pathway 16, in line with another report about epidermal stem cells." (PMID 39247819, 2024).
head and neck squamous cell carcinoma (4 papers, 2017 to 2024). A squamous cell carcinoma that arises from any of the following anatomic sites: lip and oral cavity, nasal cavity, paranasal sinuses, pharynx, larynx, and salivary glands. "Recently, down-regulated expression of ING5 mRNA was detectable in head and neck squamous cell carcinoma (HNSCC) with missense mutations located within LZL finger and NCR domains of ING5 protein." (PMID 29262575, 2017). "CAFs containing miR-196a within the cargo of EVs confer cisplatin resistance in head and neck squamous cell carcinoma (HNSCC) by targeting p27 and ING5, key regulators of cell cycle and apoptosis." (PMID 39513123, 2024).
prostate carcinoma (4 papers, 2022 to 2025). A carcinoma that arises from epithelial cells of the prostate gland. "In prostate cancer, ING5’s involvement in apoptosis, particularly in androgen-dependent and -independent prostate cancer cell lines, underscores its crucial role in tumor suppression." (PMID 38813086, 2024). "Besides, ING5 significantly downregulates prostate cancer and curbs tumor growth by inhibiting cell proliferation, clonogenicity, migration, and invasion, while promoting apoptosis." (PMID 38813086, 2024). "Several additional tumor suppressors were similarly affected by promoter-closing variants, including BBC3 (PUMA), a pro-apoptotic gene that suppresses prostate cancer cell growth, and known tumor suppressors, ATL3 and ING5." (PMID 41468516, 2025).
metastatic cancers (3 papers, 2017 to 2022). A carcinoma which has spread from the original site of growth to another anatomic site. "Cytoplasmic ING5 expression was stronger in primary cancer than that in normal tissue (p < 0.05), but weaker than the metastatic cancer (p < 0.05)." (PMID 29262575, 2017). "Nuclear ING5 expression showed gradual decrease from breast normal tissue, fibroadenoma, adenomatosis, primary to metastatic cancers, while versa for cytoplasmic ING5." (PMID 29137236, 2017). "Nuclear ING5 expression was stronger in breast normal tissue than that in fibroadenoma, adenomatosis and primary cancer (p < 0.05), adenomatosis than primary cancer (p < 0.05), and primary than metastatic cancers (p < 0.05)." (PMID 29137236, 2017). "Most notably, nuclear ING5 expression has been shown to be gradually decreased from normal breast tissue, fibroadenoma, adenomatosis, and primary cancers to metastatic cancers." (PMID 35804879, 2022).
oral squamous cell carcinoma (3 papers, 2017). "Additionally, tumor-specific mutation and downregulation of ING5 mRNA were found in oral squamous cell carcinoma." (PMID 28490335, 2017). "In addition, loss or downregulation of ING5 expression has been frequently observed in different cancer types, including head and neck squamous cell cancer, colorectal cancer, gastric cancer and oral squamous cell carcinoma." (PMID 28490335, 2017). "Recently, a low expression of ING5 mRNA was detectable in oral squamous cell carcinoma, but versa from Sun and Burat." (PMID 28915612, 2017).
osteosarcoma (3 papers, 2020 to 2022). A usually aggressive malignant bone-forming mesenchymal neoplasm, predominantly affecting adolescents and young adults. "Moreover, miR-27-3p was reported to elevate G1-S transition, causing acceleration of osteosarcoma cell growth via targeting ING5." (PMID 32308564, 2020). "By targeting ING5, miR-27-3p promotes the G1-S phase transition in osteosarcoma cells and miR-196b-5p inhibits the apoptosis of pancreatic cancer cells." (PMID 36425530, 2022).
pancreatic cancer (3 papers, 2017 to 2022). "Totally, ING5 expression was detected in 40.6% (400/986) of cancer tissues, among which ING5 was more frequently expressed in colorectal (56.3%), breast (79.9%) and endometrial (50.0%) cancers, and less in pancreatic cancer (22.6%) and HCC (14.5%)." (PMID 36425530, 2022). "MiR-196a has been well believed to be associated with abnormal apoptosis, invasion, and proliferation of pancreatic cancer cells by downregulating ING5 expression." (PMID 28466015, 2017).
squamous cell carcinoma (3 papers, 2016 to 2025). A carcinoma arising from squamous epithelial cells. "ING5 expression was different in histological classification: squamous cell carcinoma > adenocarcinoma > large cell carcinoma > small cell carcinoma." (PMID 27409347, 2016). "ING5 mRNA was overexpressed in adenocarcinoma (Ad), in comparison to squamous cell carcinoma (Sq) and small cell carcinoma (SCC, p < 0.05)." (PMID 27409347, 2016). "After transfected with pEGFP-N1-ING5, A549 (adenocarcinoma) and SQ-5 (squamous carcinoma) cells overexpressed ING5 at both mRNA and protein levels (p < 0.05)." (PMID 27409347, 2016). "Aberrant ING5 expression has been demonstrated in several cancer subtypes, for example, down-regulation of ING5 mRNA was found in squamous cell carcinoma of the oral cavity, and tumor-suppressive function of ING5 has also been found in acute myeloid leukemia (AML)." (PMID 31390718, 2019). "ING5 protein was detected in the cytoplasm and nucleus of pseudo-stratified columnar epithelium, alveolar epithelial cells, macrophage, squamous cell carcinoma, adenocarcinoma, large cell carcinoma and squamous cell carcinoma." (PMID 27409347, 2016).
thyroid cancer (3 papers, 2020 to 2024). "On the contrary, ING5 overexpression diminished the ability of proliferation and invasion in hepatocyte growth factor treated thyroid cancer cells via regulation of Akt signaling pathway." (PMID 32308564, 2020). "Furthermore, ING5 markedly reduces hepatocyte growth factor-induced proliferation, invasion, and epithelial-mesenchymal transition in thyroid cancer cells, and diminishes tumor growth and metastasis in vivo." (PMID 38813086, 2024). "ING5’s downregulation attenuates oncogenic signaling, exemplified by its counteractive effects on the c-Met/PI3K/Akt pathway in thyroid cancer." (PMID 38813086, 2024).
acute myeloid leukemia (2 papers, 2019 to 2022). Acute myeloid leukemia (AML) is a group of neoplasms arising from precursor cells committed to the myeloid cell-line differentiation. "In several cancer tissues acute myeloid leukemia (AML) and head and neck cancer, ING5 is reported to be downregulated suggesting it with anti-tumor effects." (PMID 36056353, 2022).
brain tumor (2 papers, 2023 to 2025). "We previously found that ectopic expression of ING5 increased the expression of the Oct4, Olig2 and nestin neural stem cell markers in stem-like brain tumour initiating cells (BTICS) in vitro while promoting self-renewal, preventing lineage differentiation, and increasing stem cell pools." (PMID 39787145, 2025).
breast tumor (2 papers, 2017 to 2018). "Next, we evaluated the effect of miR-24 and ING5 on the growth of breast tumors in a xenograft mouse model." (PMID 28490335, 2017). "Additionally, a recent report provides compelling data in support for a direct role of mir-24-3p in promoting breast tumor cell growth and metastasis in a xenograft mouse model via the regulation of ING5." (PMID 29560116, 2018).
Fibroadenoma (2 papers, 2017 to 2022). A benign tumor of the breast characterized by the presence of stromal and epithelial elements. "Cytoplasmic ING5 expression was higher in fibroadenoma, adenomatosis, and primary cancer than normal tissue (p < 0.05)." (PMID 29137236, 2017).